INS (insulin)
Diseases named in the same sentence as INS in open-access papers (continued):
Sharing a sentence is not in itself a finding about the gene and the disease.
Impaired glucose tolerance (continued). "Furthermore, an objective quantification of insulin sensitivity was used to ensure exclusion of individuals with impaired glucose tolerance." (PMID 34110721, 2021). "The GIPRdn transgenic pig model resembles important aspects of prediabetes, including a reduced incretin effect, impaired glucose tolerance, initially delayed and in later stages quantitatively reduced insulin secretion, and a progressive reduction of beta-cell mass." (PMID 33029223, 2020). "TMAO inhibits the hepatic insulin signaling pathway and exacerbates impaired glucose tolerance." (PMID 32082246, 2020). "Fasting insulin levels reflect the liver management of glucose in the fasting period; a prediabetes condition is characterized by an increase of fasting insulin with high insulin levels, impaired fasting glucose and impaired glucose tolerance." (PMID 32698439, 2020). "Mice selectively lacking M3 muscarinic receptor in pancreatic β cells displayed impaired glucose tolerance and a dramatic reduction in insulin secretion, demonstrating that M3 muscarinic receptor in β-cells is essential for maintaining normal glucose homeostasis." (PMID 33067534, 2020). "Similar results were observed in Sprague–Dawley rats, where MG infusion (60 mg/kg/day) for 4 weeks was associated with impaired glucose tolerance, reduced levels of the GLUT-4 glucose transporter, and decreased insulin-stimulated glucose uptake in adipose tissue." (PMID 33255888, 2020). "In particular, it should be shown whether the NZO mouse exhibits impaired glucose tolerance before and/or during pregnancy and to what extent insulin secretion is impaired." (PMID 32374082, 2020). "The chronically increased insulin demand may eventually lead to the destruction of pancreatic β cells, and consequently resulting in impaired glucose tolerance." (PMID 33008356, 2020). "Additional metabolic changes are also presented, such as increased serum TG, insulin and impaired glucose tolerance, which are consistent with clinical reports of abnormal glucose tolerance, serum insulin and lipid levels, and prepubertal ovarian enlargement in female offspring of PCOS women." (PMID 32256454, 2020). "Down‐regulated islet cell function with aging: reduced GSIR (glucose‐stimulated insulin release) and PSIR (palmitic acid‐stimulated insulin release) accompanied by the decrease of the insulin secretion peak and a gradually delayed peaking time, manifesting as obvious impaired glucose tolerance." (PMID 32232192, 2020). "The neuroprotection caused by propranolol was accompanied by a reduction in fasting glucose, fasting insulin, glucose tolerance impairment, plasma C-reactive protein, plasma free fatty acids, plasma corticosterone, brain oxidative stress, and brain inflammation." (PMID 32492962, 2020). "This showed impaired glucose tolerance and reduced insulin levels in the knockout mice." (PMID 31055616, 2019). "Impaired glucose tolerance and insulin sensitivity leads to decreased CTRP3." (PMID 31234326, 2019). "In agreement with that, a consensus statement on acromegaly therapeutic outcomes has recommended PEGV as the best medical option for patients with impaired glucose tolerance unresponsive to first-generation of SRLs, due to its beneficial effect on insulin sensitivity and glucose tolerance." (PMID 31365632, 2019). "The objective of this study was to evaluate the acute effects of two isocaloric test meals, 42 g pistachios and 100 g whole-wheat bread (WWB) on postprandial glucose, insulin, and gut derived incretin levels in Chinese women with gestational impaired glucose tolerance (GIGT) or GDM." (PMID 31921879, 2019). "However, the level rises above 110 mg/dl in the condition of impaired glucose tolerance due to insulin insufficiency or insensitivity, culminating in impaired uptake and utilization of glucose by the muscle and adipose tissues." (PMID 30847115, 2019).
Impaired glucose tolerance (continued). "One participant in the WM was diabetic (baseline glucose and insulin levels were 146 mg/dL and 77 mU/L, respectively) and another participant in the same treatment group had impaired glucose tolerance (glucose and insulin levels were 116 mg/dL and 18 mU/L, respectively)." (PMID 28702218, 2018). "Because hepatic insulin sensitivity is the most important determinant of HOMA-IR in patients with impaired fasting glucose or impaired glucose tolerance, this result suggested that hepatic insulin sensitivity is dependent on the severity of hepatic necroinflammatory activity." (PMID 29749571, 2018). "The impaired glucose tolerance at 12 weeks of age could rather be an effect of reduced insulin sensitivity as insulin secretion was increased." (PMID 30026488, 2018). "According to the proposed mechanism, TMAO may block the hepatic insulin signaling pathway, thereby exacerbating the impaired glucose tolerance, and promoting the development of fatty liver." (PMID 30551613, 2018). "Interestingly, vaspin mRNA expression was not detectable in lean subjects with normal glucose tolerance, but can be induced by increased fat mass, decreased insulin sensitivity, an impaired glucose tolerance." (PMID 28809783, 2017). "Histological analysis revealed Nuf mice to have a significant reduction in mean islet area, and these findings may have contributed to their reduced plasma insulin concentrations and impaired glucose tolerance." (PMID 28575322, 2017). "Moreover, impaired glucose tolerance and reduction in insulin sensitivity were detected after 8 and 11 weeks of HFD, respectively, with no changes in fasting glucose, suggesting alterations of glucose homeostasis compatible with a pre-diabetic stage." (PMID 28638091, 2017). "In the VA Genetic Epidemiology Study, individuals with impaired fasting glucose and impaired glucose tolerance averaged a 70% decline in pancreatic insulin secretion compared with individuals with normal glucose tolerance, after correcting for variable degrees of insulin sensitivity." (PMID 29258604, 2017). "Moreover, women with Turner syndrome are characterized by increased size of type IIa muscle fibers in addition to impaired glucose tolerance and insulin resistance, indicating diminished oxygen and substrate supply for metabolic processes." (PMID 28680878, 2017). "Thus, the use of impaired glucose tolerance and beta cell function as well as decreased insulin sensitivity as the predictors to identify individuals at high risk for T2D is important." (PMID 28713332, 2017). "A significant reduction of beta-cell β1 integrin expression in the adult mouse resulted in impaired glucose tolerance and insulin secretion, reduced beta-cell mass, decreased signaling through the FAK/ERK and Akt pathways, and diminished beta-cell function and expansion." (PMID 28968961, 2017). "Therefore, C57Bl/6 mice were fed a high-fat diet for 10 weeks, resulting in impaired glucose tolerance, diminished insulin secretion, and reduced islet size." (PMID 27512950, 2016). "In addition, following CUS, fasting insulin levels were increased and were accompanied by signs of impaired glucose tolerance and elevated serum corticosteroid levels." (PMID 27538526, 2016). "In comparison, one year treatment with metformin dosed 850 mg administered twice daily decreases the LDL particle concentration, small-sized LDL particles and slightly increases LDL size along with improvement in insulin sensitivity in subjects with impaired glucose tolerance." (PMID 26808474, 2016). "F1 offspring had impaired glucose tolerance and abnormal insulin level." (PMID 26881249, 2016).
Impaired glucose tolerance (continued). "Impaired glucose tolerance is associated with reduced insulin-stimulated whole-body glucose disposal compared with normal glucose tolerance." (PMID 26840904, 2016). "Moreover, α2-adrenoreceptor agonists inhibit lipolysis, and reduce insulin levels by inhibiting its release, which leads to impaired glucose tolerance and its increased level in blood." (PMID 26506439, 2015). "Individuals with impaired glucose tolerance (IGT) showed significant lower insulin secretion." (PMID 26398489, 2015). "Similarly, deficiency of ER chaperone ORP150 results in impaired insulin signaling and impaired glucose tolerance, while overexpression of Orp150 improves glucose tolerance and insulin signaling in obese mice." (PMID 26613076, 2015). "Normal fasting plasma glucose and insulin levels in young offspring born to the dams fed a low-protein gestational diet is reported by some studies while impaired glucose tolerance in adult female offspring due to lower insulin response to an oral glucose preload is reported by others." (PMID 26561832, 2015). "Also, injection of IFNα to healthy persons impaired glucose tolerance and insulin sensitivity, stimulated counter regulatory hormone secretion, and stimulated insulin clearance." (PMID 26441826, 2015). "Indeed, it has been previously noted that beta-cell failure precedes the development of impaired glucose tolerance (IGT) in insulin resistant subjects due to ROS induced exhaustion of the normal beta-cell capacity to adjust for increased insulin demand." (PMID 25541963, 2014). "We also measured glucose-stimulated insulin secretion to determine if this might explain the impaired glucose tolerance." (PMID 25324470, 2014). "Furthermore reduced insulin levels and impaired glucose tolerance have been observed in the FFAR2 knockout mice during an oral glucose tolerance text." (PMID 25214711, 2014). "However, despite the association of steatosis with impaired glucose tolerance, FLI and HSI seem to perform less well in insulin resistant states such as T2DM." (PMID 24732091, 2014). "It is regulated by CCAAT/enhancer binding protein (C/EBP) α and peroxisome proliferator-activated receptor (PPAR)-γ in the phosphatidyl inositol 3-kinase (PI-3 K) and mitogen-activated protein kinase (MAPK) pathways, inhibited the role of insulin in glucose uptake and impaired glucose tolerance." (PMID 24829591, 2014). "Whereas both proteins were independently (both p<1.8×10−7) associated with insulin sensitivity, circulating fetuin-A (r = −0.37, p = 0.0004), but not adiponectin, associated with insulin secretion in subjects with impaired glucose tolerance." (PMID 24643166, 2014). "HFD increased fasting glucose, fasting insulin, glucose area under curve (AUC), insulin AUC and reduced insulin sensitivity (diet effect, P<0.05) and OS and IVF mice were more susceptible to adverse effects of HFD as evidenced by impaired glucose tolerance versus NC mice (P≤0.01)." (PMID 25405530, 2014). "We did not perform glucose tolerance test or directly measure circulating levels of insulin or C-peptide in this study; as such, some participants with impaired glucose tolerance but normal fasting glucose levels could have been misclassified." (PMID 23786855, 2013). "Overexpression of let-7 reduced insulin secretion and impaired glucose tolerance in mice." (PMID 24051403, 2013). "A 10-fold increase in fasting serum insulin in female OSF vs. OC at 3 months (Insulin [pmol/L] mean ± SEM, OSF, 200.3 ± 16.1, vs. OC, 20.3 ± 1.8, n = 6 P < 0.001), was associated with impaired glucose tolerance (AUC [mmol/L min] mean ± SEM, OSF 1437.4 ± 124.2 vs. OC, 1076.8 ± 83.9, n = 6, P < 0.05)." (PMID 23423541, 2013). "In the present study, we found that AT2KO males on HFD had lesser body weight gain, lower gonadal adipose depot weight, lower levels of plasma insulin less impaired glucose tolerance (GT), higher plasma T3 and higher urinary estrogen levels, compared with HFD fed WT males." (PMID 23341867, 2013).
Impaired glucose tolerance (continued). "In this study, we investigated whether glucose and insulin levels differed among singleton and twin pregnancies and pregnancies with impaired glucose tolerance (IGT) after treatment with dexamethasone.Methods." (PMID 22536234, 2012). "Impaired glucose tolerance could result from impaired insulin production, impaired glucose-stimulated secretion (GSIS) or increased insulin resistance in liver and muscle." (PMID 22761801, 2012). "We studied the efficacy of the selected herbal preparation in subjects with impaired glucose tolerance or mild T2D because these herbs have been shown to improve insulin sensitivity and lipid metabolism which are characteristic early-phase metabolic disturbances during the development of T2D." (PMID 22474520, 2012). "In this study, we investigated whether glucose and insulin levels differ after the administration of dexamethasone among singleton and twin pregnancies and in pregnancies with impaired glucose tolerance (IGT)." (PMID 22536234, 2012). "However, at the age of 2 years, surviving diabetic animals displayed symptoms of partial spontaneous recovery with normal blood glucose and plasma insulin levels, but impaired glucose tolerance." (PMID 21792353, 2011). "Since a relevant proportion (326 out of 1782) of the participants turned out to have impaired glucose tolerance (IGT) which could confound proinsulin-to-insulin conversion, we also tested the influence of this effect." (PMID 21887289, 2011). "Glucose tolerance tests at ZT 16 were performed to determine whether the lower circulating insulin levels in ERRα-null mice at this time would result in impaired glucose tolerance." (PMID 21731503, 2011). "Short sleep duration, daytime sleepiness, and difficulty falling asleep through metabolic and endocrine dysfunctions lead to impaired glucose tolerance, increased insulin resistance, enhanced sympathetic activity, and increased blood pressure with resultant CVD." (PMID 22220186, 2011). "Taken together, these findings indicate that telomerase deficiency as found in Terc -/- G4 animals causes reduced beta-cell mass due to impaired regenerative capacity of pancreatic islets of Langerhans, culminating in impaired glucose tolerance due to reduced insulin secretion in vivo." (PMID 20876939, 2010). "First, the magnitude of the reduction in first-phase insulin release is not sufficient to cause impaired glucose tolerance in mice at this stage we examined." (PMID 21151568, 2010). "Sleep deprivation has several adverse physiological consequences, including impaired glucose tolerance and insulin sensitivity, elevated sympathetic tone, increased inflammation, and the increase of ghrelin and the decrease of leptin with the subsequent increase of hunger and appetite." (PMID 20920190, 2010). "Increasing fibre and whole grain intake affects glucose and insulin metabolism favourably and may enhance insulin sensitivity in obese subjects and in subjects with impaired glucose tolerance." (PMID 19796383, 2009). "With impaired glucose tolerance, small changes in circulating insulin also alter insulin levels." (PMID 17617917, 2007). "Since prediabetic patients with impaired glucose tolerance often suffer from reduced or lost early-phase insulin secretion, an efficient insulin mobiliser such as CAJ preload could represent a simple, easy-to-use countermeasure which does not place extra burden on pancreatic islet cells." (PMID 40238265, 2025). "Another study found that C57BL/6 mice with ovariectomy showed impaired glucose tolerance, that insulin secretion stimulated by glucose from isolated pancreatic islets was significantly reduced, and that supplementation with exogenous estradiol could salvage these effects." (PMID 40426908, 2025). "Consequently, D.welbionis J115T treatment maypartially resolve HFD-induced impaired glucose tolerance by stimulatingglucose-induced insulin secretion." (PMID 37897566, 2024).
Impaired glucose tolerance (continued). "Understanding these temporal differences is crucial, as they may indicate SB’s dual role in addressing both hepatic insulin resistance and peripheral glucose uptake, which are differently implicated in conditions such as impaired fasting glucose (IFG) and impaired glucose tolerance (IGT)." (PMID 39590851, 2024). "Therefore, the gut microbial dysbiosis observed in patients with T2DM may contribute to decreased insulin sensitivity, reduced insulin production, and impaired glucose tolerance." (PMID 39125375, 2024). "In recent years, some studies have suggested that VDD might indirectly decrease the level of intracellular calcium, thereby reducing the level of insulin secretion and beta-cellular dysfunction and, or directly reducing intracellular calcium level, as a result, impaired glucose tolerance." (PMID 38419955, 2024). "In the absence of evidence of a difference in tissue masses, hepatic or renal glucose handling, systemic or hepatic insulin resistance or renal inflammation or fibrosis, we considered alternate hypotheses to explain the impaired glucose tolerance observed in 16- to 18-week-old male RT-SAKO mice." (PMID 38280449, 2024). "Although the extent to which cell swelling contributes to insulin secretion in vivo is unknown, the observation that β cell–specific Piezo1-knockout mice exhibited impaired glucose tolerance suggests that Piezo1 may have a physiological role in insulin secretion." (PMID 37781915, 2023). "The impaired glucose tolerance might partially due to the decreased insulin levels." (PMID 36781473, 2023). "Furthermore, some pathogens, such as viruses, may directly infect pancreatic beta cells, resulting in reduced insulin secretion and impaired glucose tolerance." (PMID 37630515, 2023). "Moreover, SM not only restored the impaired glucose tolerance but also improved insulin." (PMID 35573781, 2022). "However, failure of the pancreas to mount an adequate compensatory insulinemic response (due to cortisol-mediated suppression of pancreatic insulin release) may lead to hyperglycemia and impaired glucose tolerance." (PMID 35897752, 2022). "Finally, systemic alterations in the metabolism of carbohydrates and lipids accompanied by cases of impaired glucose tolerance and insulin sensitivity are manifested by DMD patients and mouse models of the disease, including mdx mice and golden retriever muscular dystrophy (GRMD) dogs." (PMID 35273230, 2022). "In addition, administration of chlorogenic acid in subjects with impaired glucose tolerance could decrease fasting plasma glucose, elevate insulin secretion, and enhance insulin sensitivity." (PMID 34394985, 2021). "Extracellular Ca2+ can’t inflow and insulin can’t be secreted normally, which leads to a series of continuous and varying degrees of glucose metabolism abnormalities, including neonatal diabetes mellitus, impaired fasting glucose, impaired glucose tolerance and KCNJ11-MODY." (PMID 34465386, 2021). "Additionally, male Exoc5-SMKO mice had impaired glucose tolerance and lower serum insulin levels." (PMID 33647317, 2021). "Moreover, SUR1−/− male rats showed obviously impaired glucose tolerance than before and a better insulin sensitivity in the 12th week compared with females, which might be related with excess androgen secretion in adulthood." (PMID 30616503, 2019). "The observed impaired glucose tolerance and elevated blood glucose could also be a result of malfunctioning glucose transporters like Glut4 in skeletal muscle tissue, the tissue that first responds to insulin stimulation." (PMID 30728429, 2019). "However, past experimental studies conducted in healthy adults revealed that induction of low serum K, through use of high-dose diuretics or low-potassium diet and laxatives, can lead to the development of impaired glucose tolerance, through impairments in insulin secretion from pancreatic β-cells." (PMID 30169531, 2018).